FOXO1 (forkhead box O1)
Diseases named in the same sentence as FOXO1 in open-access papers (continued):
Sharing a sentence is not in itself a finding about the gene and the disease.
Obesity (129 papers, 2011 to 2026). Accumulation of substantial excess body fat. "The deficiency of FoxO1 in astrocytes disrupts glucose regulation, contributing to diet-induced obesity." (PMID 41362741, 2026). "Taken together, the observed increase in p-SMAD2/3 and FOXO1 activity associated with a decline in p-AMKα results in a reduction of mitochondrial function-related genes in obesity, thereby modulating muscle homeostasis and mass." (PMID 41272451, 2025). "Sirtuins 1 (SIRT1) and Forkhead box protein O1 (FOXO1) expression have been associated with obesity and metabolic dysfunction-associated steatotic liver disease (MASLD)." (PMID 39264516, 2024). "There is evidence that individuals harboring FOXO1 variants are associated with increased risk of developing obesity and type 2 diabetes." (PMID 35700043, 2022). "Myeloid Irs2 deficiency results in enhanced FoxO1 activity in macrophages, which impairs IL-4–induced M2 macrophage activation and predisposes to developing dietary obesity and hyperinsulinemia in mice." (PMID 35700043, 2022). "By lowering FoxO1 acetylation and protein levels, SIRT1 prevents obesity caused by the insulin-unsusceptible vital nuclear location of FoxO1 in pro-opiomelanocortin (POMC) neurons in male mice." (PMID 33804729, 2021). "Mice with constitutively active nuclear FoxO1 have elevated food intake and associated obesity, while mice with deletion of FoxO1 in hypothalamic neurons have diminished food intake." (PMID 33845179, 2021). "At the molecular level, obesity is associated with impaired Akt activity, enhanced NF-κB and FoxO1, and increased TNF-α and IL-6 levels, all of which are related to muscle atrophy." (PMID 35010979, 2021). "In animal studies, overexpression of FOXO1 in both the hypothalamus and pancreas causes obesity, glucose intolerance and decreased insulin sensitivity." (PMID 31156786, 2019). "Compelling observational evidence indicates that endothelial FoxO1 dysregulation coincides with obesity-associated metabolic disturbances." (PMID 30511639, 2018). "Data indicate that the progression of obesity is linked with FoxO1." (PMID 33804729, 2021). "This study demonstrated that MLB supplementation attenuated obesity-associated skeletal muscle atrophy in HFD mice through the regulation of the PI3K/Akt/FoxO1 and TNF-α/NF-κB signaling pathways, leading to the inhibition of muscle-specific ubiquitin E3 ligase expression." (PMID 35010979, 2021). "Growing research also shows that through FoxO1, microRNAs (miRs) perform lipid-regulating mechanisms, which suggest that FoxO1 could be implicated in the genetic changes implicated in obesity." (PMID 33804729, 2021). "This compound increases expression of genes associated with lipid metabolism such as SIRT1, FOXO1 and PPARγ and could therefore be considered for the treatment of obesity and metabolic impairment." (PMID 33806509, 2021). "Although this suggests that the interplay between endothelial FoxO1 levels and EC metabolic activity may be critically implicated in limiting vascular remodeling in obesity, this concept demands validation." (PMID 30511639, 2018). "Induction of hepatic FoxO1 expression may provide an effective strategy for raising hepatic triglyceride catabolism, thereby probably preventing hepatic triglyceride accumulation and obesity-associated NAFLD." (PMID 33449950, 2021). "This demonstrates that endothelial FoxO1 is a prime regulator of adipose tissue microvascular remodeling in adult mice, underlining our hypothesis that FoxO1 levels are directly implicated in limiting the angiogenic response of ECs in obesity." (PMID 30511639, 2018). "Over the past 25 years, Foxo1 has evolved from a liner insulin effector to a pleiotropic integrator of systemic metabolic stress during obesity and aging." (PMID 41597184, 2026). "FOXO1′s role inducing inflammation in several tissues, especially adipose tissue, also adds to chronic low-grade inflammation, an obesity characteristic." (PMID 40218884, 2025).
Obesity (continued). "Western blot and qPCR showed that the induction of obesity-related SAP significantly decreased the expression of FoxO1 in adipose tissue." (PMID 40806352, 2025). "Hypothalamic iron accumulation promotes age-dependent obesity by increasing mitochondrial ROS and driving FoxO1 nuclear translocation, which upregulates AgRP expression and disrupts energy homeostasis." (PMID 41037185, 2025). "We found that depleting endogenous ovarian hormones blocked the anti-obesity effects of FoxO1-KOMPOA on both body weight and food intake during HFD feeding, suggesting that ovarian hormones are necessary for the sex-specific anti-DIO effects of FoxO1-KOMPOA." (PMID 40667056, 2025). "In terms of metabolisms, Mib2 promoted PTEN proteasomal degradation to inhibit FoxO1‐dependent Ucp1 (Uncoupling protein‐1) transcription in brown adipose tissue, which triggers obesity." (PMID 40159625, 2025). "Here, we show that iron overload-induced ROS activate hypothalamic FoxO1, increasing AgRP expression and promoting age-dependent obesity, revealing a central role for this pathway in energy balance." (PMID 41037185, 2025). "A further examination in the current study demonstrated a decreased expression of FoxO1 in obesity-related SAP." (PMID 40806352, 2025). "By modulating FOXO1, anthocyanins not only improve insulin sensitivity but also mitigate the adverse effects of obesity on glucose and lipid metabolism." (PMID 40218884, 2025). "In conclusion, FOXO1 plays an important regulatory role in various pro-inflammatory and glucose signaling pathways, suggesting that FOXO1 is a valuable therapeutic target for the treatment of obesity." (PMID 38674793, 2024). "mRNAs of PPAR‐γ and as well, FOXO1, FOXO3 and PTEN are targets of miR‐320a and miR‐486‐5p, respectively, and are associated to insulin metabolism and related conditions such as obesity and dyslipidemia." (PMID 37329278, 2023). "Accordingly, PDK1 inhibits FoxO1 to regulate macrophage infiltration, and the PDK1/FoxO1 pathway in macrophages is essential for regulating macrophage polarization and insulin sensitivity in obesity." (PMID 37153549, 2023). "Overall, evidence suggests that FoxO1 inhibition in the hypothalamus has the potential to treat obesity induced T2D." (PMID 37941908, 2023). "These miRNAs were suspected to target the molecules including STAT3, PI3K, AKT and FOXO1 in leptin signal in obesity, PPARγ and FOXO1 in adipogenesis pathway, and p38MAPK, PPARγ and PPARα in white adipose tissue browning pathway." (PMID 36065413, 2022). "FOXO1, a transcription factor which is known to enhance proinflammation, was recently shown to be involved in obesity-induced β cell dysfunction." (PMID 35198097, 2022). "Hepatic insulin resistance in the context of obesity increases the nuclear localization of FOXO1 and the expression of its gluconeogenic and lipogenic gene targets, driving up VLDL-TAG secretion." (PMID 36111295, 2022). "The role of FOXO1 in inflammatory and metabolic disorders has been widely investigated, while its function in obesity-induced β cell dysfunction during the development of T2MD remains to be elucidated." (PMID 35198097, 2022). "FOXO1 mediated leptin on food intake and the central leptin–melanocortin pathway played a pivotal role in the regulation of obesity by ADCY3." (PMID 36101325, 2022). "In conclusion, our studies based on INS-1E cells in vitro have clarified the molecular mechanism of TNF-α aggravating obesity-related β cell dysfunction and described a novel function of FOXO1 involved in TNF-α-induced LepRb reduction of INS-1E cells." (PMID 35198097, 2022). "To characterize the role of FoxO1 in macrophage activation and hepatic inflammation in obesity, we fed male C57BL/6 mice a high-fat diet (HFD, n = 6) or regular chow (RC, n = 6) for 8 weeks." (PMID 35700043, 2022). "Observing the dissociation of CtBP2 from FoxO1 in obesity, a question arises regarding in which cellular compartment this regulatory step occurs." (PMID 34728642, 2021).
Obesity (continued). "Various transcriptional factors such as Forkhead box O1 (FoxO1) impart a significant effect on the physiology and pathology of metabolic dysfunction such as obesity." (PMID 33804729, 2021). "In mice with genetic obesity, CtBP2/FoxO1 interaction was dramatically (~90%) reduced as well as in diet-induced obese mice." (PMID 34728642, 2021). "A2AR ligation additionally enhances in vivo activation of FoxO1 and FoxO3 with evidence of enhanced autophagic flux upon injection of the liposome-associated A2AR agonist in a mouse obesity-induced OA model." (PMID 33441836, 2021). "FOXO1 levels are elevated in obesity, and mice with reduced endothelial expression of FOXO1 had improved vascular remodelling in AT and enhanced glucose tolerance." (PMID 33292104, 2020). "FoxO1 is recognized as an “anti-obesity” factor able to improve adipose metabolism and fat mobilization upon its fundamental stimulus that is the lack of nutrients." (PMID 32244542, 2020). "Selectively inhibiting FTO by inhibitors decreases FOXO1 expression and reduces body weight and fat mass in a high-fat diet-induced obesity (DIO) mouse model." (PMID 31936903, 2020). "The regulation of FoxO1 to β‐cell compensation to overnutrition and obesity was thereafter disrupted by the FoxO1 deacetylation failure in the diabetic patients harboring HDAC4 mutations." (PMID 30968599, 2019). "Here, using yeast two-hybrid screening, we show that Zfp238 is a Foxo1 co-repressor and that adipose-tissue-specific ablation of Zfp238 (Adipo-Zfp238KO) in mice leads to obesity, decreased energy expenditure, and insulin resistance under normal chow diet." (PMID 30677742, 2019). "Parallelly, as downstream protein of PI3K pathway and transcription factor of G6PC, FOXO1 was detected to be decreased in obesity group and confirmed via qPCR with AUC = 0.8." (PMID 31824561, 2019). "More importantly, these findings indicate FoxO1 as a central target for the manipulation of capillary EC response to obesity-induced conditions." (PMID 30511639, 2018). "Exercise can also increase insulin and its downstream protein expressions in the myocardium of diet-induced obesity rats, as well as forkhead box protein o1 (Foxo1) and other key regulators of pancreatic β cells, and also activate insulin signaling pathway." (PMID 30559720, 2018). "Herein, we provide evidence that endothelial FoxO1 is critical to the development of metabolic disorders in obesity through the converging actions of controlling metabolic activity and angiogenic fate of the endothelium." (PMID 30511639, 2018). "To further investigate the mechanism by which zerumbone regulates the miR-146b/SIRT1 axis to reduce obesity and adipogenesis, we analyzed its effect on the acetylation of FOXO1 and PGC1-α, two downstream targets of SIRT1." (PMID 28445161, 2017). "The importance of the MKP-3 phosphatase activity on FoxO1 and Erk1 2 is well described; therefore, we evaluated the phosphorylation of these proteins in the obesity condition." (PMID 29062272, 2017). "Given that obesity is linkedto dysregulation of FoxO1,2,41 autophagy and UCPs,5,10–12 furtherstudies of the FoxO1-autophagy-UCPs axis will advance our understanding of obesity and itsrelated metabolic disorders." (PMID 27777789, 2016). "Apart from common DIS regulated genes the transcription factors FOXO1 and FOXA2 and the insulin induced gene 2 are specific targets of miR-335-5p; note polymorphisms of INSIG2 are associated with severe obesity." (PMID 27045805, 2016). "Further, activation of SIRT1 using a synthetic molecule protects mice from diet-induced obesity and increases lipid oxidation in the skeletal muscle by mediating the deacetylation of PGC1α and FOXO1." (PMID 23024761, 2012). "In this study, we investigated whether maternal obesity alters stemness, redox homeostasis and adipogenic signaling through FOXO1 in neonatal MSCs." (PMID 42047265, 2026).
Obesity (continued). "Furthermore, the inhibition of FoxO1 aggravated the impaired autophagic flux in ATMs during obesity-related SAP and contributed to more severe inflammatory injuries." (PMID 40806352, 2025). "FOXO1 inhibits skeletal muscle growth and protein synthesis by inhibiting the activity of essential anabolic pathways, such as mTORC1, leading to muscle wasting and impaired glucose metabolism in obesity." (PMID 40218884, 2025). "We also found that phosphorylated FoxO1 increased after the induction of obesity-related SAP." (PMID 40806352, 2025). "Several studies have suggested that Sirtuin 1 (SIRT1) and Forkhead box protein O1 (FOXO1) could play a role in lipid metabolism in obesity and MASLD in rodents." (PMID 39264516, 2024). "This system may be significantly impaired in obesity, because obesity can disrupt circadian fluctuations in the plasma eNAMPT−hypothalamic NAD+-FOXO1 axis." (PMID 39766263, 2024). "Finally, we aimed to study the effects of a 16-week intervention with a DHA-rich n-3 PUFA supplementation alone or in combination with a RT program on the changes of SIRT1 and FOXO1 mRNA expression in PBMC from postmenopausal women with overweight/obesity." (PMID 39264516, 2024). "However, EC-specific deletion of FoxO1 prevents obesity-related disorders by increasing vascular glycolysis, proliferation, and growth." (PMID 36394956, 2023). "Furthermore, the administration of synthetic adropin promotes glycogen synthesis, attenuates glucose production, and improves insulin sensitivity by raising IRS1/2-Akt phosphorylation and lowering the FoxO1 transcript in mouse models of diet-induced obesity." (PMID 37079136, 2023). "Several mechanisms are known for miR-144-3p to promote adipogenesis: from suppressing the FOXO1 and reducing its regulation of adiponectin to stimulating differentiation of adipocytes by direct targeting Klf3 and CtBP2, protective factors against obesity." (PMID 38139235, 2023). "In summary, IL-6 deficiency does not protect against early postnatal obesity but prevents FoxO1 inactivation and bronchial and lung microvascular SMC hyperproliferation, thereby preventing bronchial and vascular remodeling after maternal and perinatal obesity." (PMID 35896539, 2022). "Therefore, we stained lung tissues of mice after maternal and perinatal obesity (HFD) as well as control mice (SD) at P21 to detect both FoxO1 and αSMA." (PMID 35896539, 2022). "As the phosphorylation of an insulin receptor substrate 1 (IRS-1)/phosphoinositide 3-kinase (PI3K)/Akt and downstream signaling pathways, forkhead box protein O1 (FOXO1), and glycogen synthase kinase 3β (GSK3β) are modulated by THC to decrease the risk of obesity." (PMID 36263142, 2022). "Consistent with this hypothesis, FoxO1 and Stat6 are reciprocally regulated, culminating in increased FoxO1 activity and decreased Stat6 activity in activated macrophages in obesity and type 2 diabetes." (PMID 35700043, 2022). "Thus, in the current study, will be discussed the dual role of FoxO1 in metabolic conditions (such as obesity), also summarizing the role of various other transcriptional factors involved in obesity." (PMID 33804729, 2021). "Finally, FoxO1 plays a pivotal role in ameliorating fat metabolism, maintaining redox homeostasis and thus counteracting pathologies such as obesity and type II diabetes." (PMID 32244542, 2020). "On the contrary, in the setting of obesity/T2D, increased myocardial forkhead box O1 (FoxO1) may contribute to increased PDHK4-mediated inhibition of PDH activity and subsequent glucose oxidation." (PMID 33041869, 2020). "These suggested that pharmacological inactivation of FoxO1 may be used to suppress appetite and treat obesity." (PMID 31936903, 2020). "For instance, the activation of PPAR-γ2, which cannot be blocked by FOXO1, may up-regulated IGFBP-2 expression to protect adipocyte cells towards metabolic alterations associated with obesity." (PMID 31547433, 2019).
Obesity (continued). "Therefore, both Zfp238 and Foxo1 in adipocytes should be molecular targets for the prevention and treatment of obesity." (PMID 30677742, 2019). "We demonstrated that Zfp238 inhibits Foxo1 transcriptional activity and that adipose-tissue-specific Zfp238 knockout mice (Adipo-Zfp238KO) show obesity, decreased whole-body O2 consumption, and decreased expression of Ucp1 stimulated with cold exposure or β3 agonist in subcutaneous adipose tissue." (PMID 30677742, 2019). "The converging roles of FoxO1 in the angiogenic phenotype and the metabolism of quiescent EC led us to hypothesize that FoxO1 is a critical nodal point in determining the response of capillary EC to obesity." (PMID 30511639, 2018). "Further, clinical analysis on the expression pattern of FoxO1 and SF-1 in patients with obesity and type 2 diabetes could shed more light on the relationship between HPA axis dysregulation and obesity development." (PMID 29567944, 2018). "Taken together, our study reports that obesity is associated with increased protein levels of hypothalamic MKP-3, which is related to the reduction of FoxO1 and Erk1/2 phosphorylation in the hypothalamus as well as to an increase in body weight and a reduction in energy expenditure." (PMID 29062272, 2017). "Therefore, taking our results together, the MKP-3 increased in the hypothalamus, at least in part, contributing to the insulin signaling pathway impairment due to its effect on FoxO1 and Erk dephosphorylation, which induce hyperphagia and obesity in animals." (PMID 29062272, 2017). "It has been identified that calcium calmodulin-dependent kinase II has profound effect on FOXO1 nuclear retention, which may lead to excessive glucose production in the liver, in the context of obesity." (PMID 26956801, 2016). "Therefore, we postulated that the improved glucose/insulin sensitivity and resistance to diet-induced obesity in FoxO1 KODAT mice were due, at least in part, to decreased food intake." (PMID 27681312, 2016). "Additionally, elevated aPKC activity was shown to attenuate AKT-dependent FOXO1 phosphorylation in the liver of diet-induced obesity mice, despite concurrent elevated hepatic AKT activity." (PMID 25822413, 2015). "Thus, the pronounced anti-obesity effects seen in female FoxO1-KOMPOA mice during HFD feeding likely represent the disruption of this female-specific energy conservation mechanism, underscoring FoxO1MPOA’s crucial role in sex-specific metabolic adaptation to an energy surplus condition." (PMID 40667056, 2025). "Moreover, FoxO1 may play a role in contributing to airway fibrosis in individuals with asthma and obesity." (PMID 38562155, 2024). "Obesity-induced airway fibrosis may involve the role of FoxO1." (PMID 38562155, 2024). "Considering this crucial point, FoxO1 may play a role in obesity-induced airway remodeling." (PMID 38562155, 2024). "As a result, FOXO1 could be a promising target for anti-obesity treatment." (PMID 38674793, 2024). "However, whether FXR or Foxo1 is involved in activating Fetuin B in the context of obesity requires further investigation." (PMID 35896788, 2022). "Liver autopsy samples showed diminished CtBP2/FoxO1 interaction in the liver of subjects with obesity, suggesting that our findings could be extrapolatable and relevant to human disease despite the imperfect qualities of samples related to the postmortem changes." (PMID 34728642, 2021). "Differences in obese compared with non-obese may also relate to the rate-limiting enzyme of bile acid synthesis, cholesterol 7α-hydroxylase (CYP7A), whose basal expression is increased in an obesity mouse model via both glucose-stimulated epigenetic modifications and the insulin/FoxO1 pathway." (PMID 26863521, 2016).